TIMP1 (TIMP metallopeptidase inhibitor 1)
Diseases named in the same sentence as TIMP1 in open-access papers (continued):
Sharing a sentence is not in itself a finding about the gene and the disease.
preeclampsia (10 papers, 2015 to 2025). Preeclampsia is a hypertensive disorder of pregnancy that is characterized by new-onset hypertension with proteinuria presenting after 20 weeks of gestation, and depending on mild or severe forms may initially present with severe headache, visual disturbances, and hyperreflexia. "The present results indicate a relationship between TIMP1 rs4898 (372T > C) polymorphism and increased risk of early-onset preeclampsia (EOPE) in a population of pregnant Polish women." (PMID 35885543, 2022). "The authors found that TIMP1 −9830T>G polymorphism is associated with preeclampsia (association with PE in carriers of the G allele as well as the GG genotype)." (PMID 35885543, 2022). "There were lower MMP-9 levels and MMP-9/TIMP-1 ratios in gestational hypertension patients with the GG genotype for the TIMP-1 polymorphism than in those with the TT genotype." (PMID 33803206, 2021). "Moreover, two studies were conducted for TIMP1 and TIMP3 gene polymorphisms in preeclampsia and showed the association for TIMP1 rs20705558 and TIMP3 rs80272 polymorphisms." (PMID 35885543, 2022). "The stratified analysis showed in the recessive model CC + CT genotype frequency 85.5% in the EOPE and 70.0% in the LOPE subgroup (OR = 2.52, p = 0.0452) which suggests that TIMP1 rs4898 could be associated with the form of preeclampsia." (PMID 35885543, 2022). "The decrease in MMP-2 and MMP-9 activity or ratios of MMP-2/TIMP-2 and MMP-9/TIMP-1 might be involved in the pathogeneses of early pregnancy loss and preeclampsia." (PMID 33796532, 2021). "Interestingly, gene–gene interaction analysis showed that the GG genotype for the rs2070584 SNP of TIMP1 was associated with preeclampsia and with responsiveness to total antihypertensive therapy in preeclampsia depending on genotypes for the rs3801266 SNP (A/G) of NAMPT gene." (PMID 29541029, 2018). "This study aimed to assess the potential role of MMP1, MMP9, TIMP1 and TIMP2 gene polymorphisms in the pathogenesis of preeclampsia." (PMID 35885543, 2022). "Higher TIMP-1 levels were found in PE as compared with gestational hypertension (GH) and normotensive pregnant women." (PMID 33803206, 2021). "The authors reported weak positive correlations between maternal age and TIMP-1 in the gestational hypertension group and between gestational age and TIMP-2 in the control group." (PMID 33803206, 2021). "They reported an imbalance in the MMP-2/TIMP-1 ratio at all three gestational time points in patients who subsequently developed preeclampsia." (PMID 33803206, 2021). "Several studies show that MMP-9 increases along both, normal and preeclampsia-complicated pregnancy, while its inhibitor TIMP-1 increases in preeclamptic vs. normal pregnant women." (PMID 28726716, 2017). "Preeclampsia TG genotype patients had elevated levels of TIMP-1." (PMID 33803206, 2021). "However, further research into the molecular mechanisms underlying the interactions among NAMPT, TIMP1 and MMP2 and their relationship with the response to antihypertensive therapy in preeclampsia is needed." (PMID 29541029, 2018). "The aim of the present study was to explore the levels of matrix metalloproteinase-1 (MMP-1) and tissue inhibitor of metalloproteinase-1 (TIMP-1) in the maternal umbilical serum, placenta and decidua of patients with preeclampsia compared with those in normotensive pregnant females." (PMID 25667666, 2015). "However, the positive rates of expression of TIMP-1 in the placenta of the normal, gestational hypertension, mild preeclampsia and severe preeclampsia groups were 56.7, 61.1, 66.7 and 75.0%, respectively." (PMID 25667666, 2015). "Our data suggest that the TIMP1 rs4898 C allele might be associated with increased risk for early-onset, but not for late-onset preeclampsia." (PMID 35885543, 2022). "Our data suggest that the TIMP1 rs4898 C allele might be associated with increased risk for early-onset, but not late-onset, preeclampsia." (PMID 35885543, 2022).
preeclampsia (continued). "Notably, the GG genotype, and the G allele, of the rs2070584 (T/G) SNP of TIMP1 gene were associated with both the disease and with the patients with preeclampsia who were non-responsive to antihypertensive therapy." (PMID 29541029, 2018). "In preterm preeclampsia, PlGF and VEGFR-1 displayed a differential abundance in both soluble and EV fractions, whereas angiogenin, CD40L, endoglin, galectin-1, and TIMP1 were changed only in the soluble fraction." (PMID 41515555, 2025). "The results indicated low levels of expression of TIMP-1 and TIMP-2 in the gestational hypertension group." (PMID 33803206, 2021). "Even though most evidence links increased circulating levels of MMP-9 and -2 with preeclampsia, two interesting reports show that pro-MMP-9, MMP-9 and MMP-9/TIMP-1 ratio remain unchanged in preeclamptic pregnancies in the Brazilian population." (PMID 28726716, 2017). "Plasma TIMP-1 in non-pregnant subjects was significantly higher than both normotensive pregnant and gestational hypertension subjects." (PMID 33803206, 2021). "Cardiac gene expression of Vcam, Edn1, Ccr2, Ctgf, Tgfb1, Tgfb2, Tgfb3, Bnp, Cybb, Mmp2, Mmp9, Timp1, Camk2a, Slc9a1, Nr3c2, and Nr3c1 was not different between mice who had a normal pregnancy and mice who had a preeclampsia-like pregnancy at 5 or 10 weeks postpartum (respectively)." (PMID 40425613, 2025).
schizophrenia (10 papers, 2010 to 2024). A major psychotic disorder characterized by abnormalities in the perception or expression of reality. "Schizophrenia is associated with higher MMP-9/TIMP1 ratios compared to healthy controls." (PMID 30123106, 2018). "For instance, age effects do not appear to modify substantially the highly significant associations found for BDNF, RANTES, EGF, TIMP-1, ENA-78 and MDC levels with schizophrenia." (PMID 20161799, 2010). "In fact, in Rahimi’s study, MMP-9 and TIMP-1 are involved in neurotransmission processes and are strong candidates for the appearance of positive symptoms and negative symptoms, as well as cognitive dysfunction typical of schizophrenia." (PMID 38254696, 2024). "The concentrations of IL-1Ra, tissue-inhibitor of metalloproteinase-1 (TIMP-1), and TIMP-2 in the schizophrenia group were decreased (all P < 0.001)." (PMID 35223927, 2022). "An unbiased approach in screening altered levels of plasma proteins in patients with schizophrenia also revealed increased levels of MMP-9 and TIMP-1." (PMID 31172215, 2019). "Our finding of increased TIMP1 and decreased MMP1 is consistent with previous reports and suggests a cytoprotective role of this pathway in the brains of schizophrenia patients." (PMID 23118852, 2012). "This showed that 9 of the analytes (C-reactive protein, cortisol, resistin, TIMP-1, chromogranin A, VEGF, thrombopoetin, alpha-2 macroglobulin, and glutathione S-transferase) were also found to be reproducibly altered between schizophrenia and control subjects in serum." (PMID 23118852, 2012). "Three additional schizophrenia-related genes were not examined by PCR-array, but, based on previous microarray studies, are already known to be significantly up-regulated in medial rectus muscles from patients with exotropia: CTGF, TIMP1 and TIMP2." (PMID 29302405, 2017).
steatosis (10 papers, 2015 to 2024). Increased lipid within the cytoplasm of cells. "In fibrotic NASH patients, 12 weeks of cilofexor reduced steatosis, transaminases and TIMP1 levels, which was confirmed in a 24-week phase 2 randomized placebo-controlled trial." (PMID 33435509, 2021). "TIMP1 also had the greatest ability to discriminate microvesicular steatosis among the serum biomarkers (AUC: 0.48)." (PMID 32150543, 2020). "In binary logistic regression analysis, the biologics (group), disease activity, disease duration, age, adiponectin, TNF, leptin, PIIINP, and TIMP-1 were sequentially entered as potential confounders, with the dependent variable being the presence of steatosis, based on the Hamaguchi score." (PMID 39598344, 2024). "Inflammation, steatosis, ballooning, and fibrosis are the features of non-alcoholic fatty liver disease (NAFLD), and the associated critical bona fide genes such as MCP-1, TNF, TNFR1, TGFβ1, Colα1, αSMA, Timp1, and Hp were significantly enriched in the livers of mice fed an HFD." (PMID 31616013, 2019). "Furthermore, the expression of the fibrosis-related genes Col1a1, Tgfb1, and Timp1 was lower in the HY7207 group than in the ND group These data imply that HY7207 ameliorates hepatic lipid accumulation, steatosis, inflammation, and fibrosis in mice with NAFLD." (PMID 39337360, 2024). "Here we showed that, despite lower steatosis in MCD-fed MyMRKO mice, the histological and molecular features of fibrosis remain unaffected by MR deletion in myeloid cells (including higher levels of profibrotic markers Col1A, Mmp-2, Timp-1, and Tgfβ)." (PMID 33391254, 2020).
tuberculosis (10 papers, 2009 to 2023). A chronic, recurrent infection caused by the bacterium Mycobacterium tuberculosis. "Concentrations of matricellular proteins tenascin C and TIMP-1 were increased in patients with HIV-tuberculosis, and higher concentrations were associated with decreased survival time." (PMID 28363198, 2017). "MMP9 and Timp1 are known to be up-regulated in tuberculosis infection and have been proposed as biomarkers for diagnosis of tuberculosis." (PMID 32881863, 2020). "Mmp9 and Timp1 are known to be up-regulated in tuberculosis infection and have therefore been proposed as biomarkers for diagnosis of tuberculosis." (PMID 28542507, 2017). "This is in agreement with findings of previous studies that have demonstrated increased levels of tenascin C and TIMP-1 in patients with active tuberculosis, with even higher concentrations measured at the site of infection." (PMID 28363198, 2017). "Moreover, in tuberculosis, 1,25(OH)2D3 was shown to suppress the production of MMPs while enhancing TIMP-1 levels." (PMID 37299440, 2023). "Our findings show that M. tuberculosis stimulation of PBMCs differentially increased the transcript levels for MMP-1, MMP-7, MMP-10, and TIMP-1 genes in paradoxical TB-IRIS participants in 24 h cultures (pcorr ≤ 0.05) compared with non-IRIS controls." (PMID 24136296, 2014). "Concentrations of tenascin C and TIMP-1, both markers of matricellular metabolism, were higher in patients with HIV-tuberculosis." (PMID 28363198, 2017). "Of note MMP-3, -8, -9 and TIMP-1 fell and TIMP-4 rose significantly over the course of 9 months anti-tuberculosis treatment." (PMID 19789647, 2009). "IFN-γ, IL-1β, TIMP-1, and TIMP-2 could also be prognostic markers of the course of tuberculosis." (PMID 37686061, 2023). "Thus, IFN-γ, IL-1β, TIMP-1, and TIMP-2 could be prognostic markers of the course of tuberculosis, and proteins involved in the regulation of their synthesis could be potential targets in the pharmacotherapy of the disease." (PMID 37686061, 2023). "Type I collagen had minimal effects on TIMP-1 secretion, which is increased by M. tuberculosis stimulation, or on TIMP-2 secretion, which was decreased by TB." (PMID 28646039, 2017). "TIMP genes were generally not regulated by M. tuberculosis at mRNA and cell culture supernatant levels, although TIMP-1 was found to be elevated in the serum of TB-IRIS participants." (PMID 24136296, 2014).
abdominal aortic aneurysm (9 papers, 2011 to 2025). Enlargement and ballooning of the vessel that supplies arterial blood to the abdomen, pelvis and legs. "It has been reported that the polymorphisms of MMP-3 promoter and TIMP-1 gene are related to abdominal aortic aneurysm." (PMID 37575991, 2023). "However, a silent SNP Phe124Phe of TIMP-1 gene had been reported to be associated with abdominal aortic aneurysm in women." (PMID 23226977, 2012). "The increase in TIMP1 expression may help prevent the development of abdominal aortic aneurysms in a healthy animal by inhibiting degradation of ECM structural proteins." (PMID 33101359, 2020). "The activation of MMP-9 and the TIMP-1 inactivation by HNE have important physiopathological role in cystic fibrosis lung disease, intracranial hemorrhage, abdominal aortic aneurysm and bone resorption." (PMID 21731773, 2011). "Delivery of mRNA to increase the TIMP-1 ratio improves ECM integrity in animal models of abdominal aortic aneurysm; however, no literature exists on TIMP supplementation in IAs." (PMID 41155344, 2025). "In addition, a recent study noted that knockdown of PVT1 decreased levels of MMP-2 and MMP-9, augmented TIMP-1 expression, and suppressed serum levels of TNF-α, IL-1β, and IL-6 in VAMC and ApoE-/- mice of abdominal aortic aneurysm model." (PMID 34775377, 2021). "Indeed, MMP-9/TIMP-1 imbalance has been observed in sputum of patients with cystic fibrosis and in abdominal aortic aneurysm; where the high level of HNE promotes a large MMP-9 activation either directly or by the proteolysis of TIMP-1, its natural inhibitor." (PMID 21731773, 2011).
aortic aneurysm (9 papers, 2004 to 2025). A ruptured aneurysm located in the wall of the proximal portion of the descending aorta proceeding from the arch of the aorta. "TIMP1 is found to be increased in the vessel wall of aortic aneurysms, but in the intima, it is stimulated by TNFα." (PMID 38540232, 2024). "Overexpression of TIMP-1 expression results in reduction in plaque area in apoE−/− mice and ease of aortic aneurysm degeneration and rupture in rat model 41,42." (PMID 25661015, 2015). "Additionally, the implementation of genetic testing to identify genes associated with malformations (ZFYVE9, TIMP1, PRKX, KDM6A) can lead to a higher detection rate of aortic aneurysm formation, congenital urinary malformations and other anomalies." (PMID 29537378, 2018). "We point to candidate genes of comorbidity in TS e.g. congenital urinary malformations (PRKX), premature ovarian failure (KDM6A) and aortic aneurysm (ZFYVE9 and TIMP1)." (PMID 27687697, 2016). "We describe novel candidate genes that could be involved in comorbidity in TS and explain congenital urinary malformations (PRKX), premature ovarian failure (KDM6A), and aortic aneurysm formation (ZFYVE9 and TIMP1)." (PMID 27687697, 2016).
diabetic foot ulcers (9 papers, 2008 to 2026). "The MMP-1/TIMP-1 ratio is a predictor of wound healing in diabetic foot ulcers." (PMID 18387077, 2008). "TIMP1, tissue inhibitor of metalloproteinase-1, plays an important role in balancing the TIMP1/MMPs ratios which may represent potential biomarkers for predicting the clinical morbidity of diabetic foot ulceration patients as well." (PMID 28423369, 2017).
diabetic retinopathy (9 papers, 2016 to 2025). "Studies have demonstrated that TIMP1 and A2M expression is increased in the eyes of patients or animals with diabetic retinopathy." (PMID 29318137, 2017). "Consistent with the results presented here, homocysteine suppresses the transcription of a tissue inhibitor of matrixmetalloproteinase-9, Timp1, by hypermethylating DNA at its promoter, increasing mitochondrial damage, and it also accelerates the development of diabetic retinopathy." (PMID 38539790, 2024). "Taken together, these results indicated that SOCS3-STAT3 and TIMP1-A2M pathways might mediate the alleviation of HXJD activities in rats with diabetic retinopathy." (PMID 29318137, 2017). "have pinpointed six significant genes (CD44, CDC42, TIMP1, BMP7, RHOC, FLT1) as crucial for diabetic retinopathy through advanced bioinformatics analysis coupled with in vivo validation." (PMID 38605967, 2024).
epilepsy (9 papers, 2014 to 2023). A brain disorder characterized by episodes of abnormally increased neuronal discharge resulting in transient episodes of sensory or motor neurological dysfunction, or psychic dysfunction. "One mechanism thought to underlie epilepsy progression may be through a change in the ratio of MMP-9 to TIMP-1, the endogenous inhibitor of MMP-9." (PMID 26283917, 2015). "A sequential increase in TIMP-1 expression, first in neurons and after 3 days in astrocytes, was showed in a model of kainate-induced epilepsy." (PMID 36766708, 2023). "Subjects with varying forms of epilepsy have an increase in the MMP-9/TIMP-1 ratio suggesting an increase in the extracellular levels of MMP-9 activity." (PMID 26283917, 2015). "Matrix metalloproteinases were initially identified as critical for brain function because the mRNA for TIMP1, an endogenous inhibitor of MMPs, is upregulated in a kainic acid-induced epilepsy model, suggesting an activity-dependent role for MMPs in epilepsy." (PMID 25368556, 2014). "The molecules whose levels are chronically elevated in serum of patients with epilepsy (MMP-2, MMP-9, S100B, TIMP-1, TIMP-2) might be considered diagnostic biomarkers of epilepsy." (PMID 36766708, 2023). "TIMP1, the most significant IRG associated with TLE, might be a novel and promising biomarker to study the mechanism of epilepsy and guide the discovery of new drugs for its treatment." (PMID 37365625, 2023). "Moreover, qRT‒PCR and western blotting indicated that TIMP1 was decreased in the cortices and hippocampi of KA-induced epilepsy mice compared with controls." (PMID 37365625, 2023). "In conclusion, we identified TIMP1 as the most significant IRG associated with epilepsy and found the downregulated expression of TIMP1 in epileptic patients and mice, which may provide new ideas for studying the mechanism of epilepsy and discovering new drugs for treatment." (PMID 37365625, 2023). "Serum levels of MMP-9, MMP-2, TIMP-1, TIMP-2 and S100B are elevated in patients with epilepsy in the interictal period, which suggests chronic processes of BBB disruption and restoration." (PMID 36766708, 2023). "Serum levels of MMP-9, MMP-2, TIMP-1, TIMP-2 and S100B were higher in patients with epilepsy in comparison to control group (p < 0.0001; <0.0001; 0.001; <0.0001; <0.0001, respectively)." (PMID 36766708, 2023). "Serum levels of MMP-9, MMP-2, TIMP-1, TIMP-2, S100B, CCL-2, ICAM-1, P-selectin, and TSP-2 were examined in a group of 49 patients with epilepsy who were seizure-free for a minimum of seven days and measured by ELISA." (PMID 36499038, 2022). "More studies should be conducted to further examine the function of CD44, TIMP1, and SERPINE1 in epilepsy." (PMID 33225612, 2020). "A set of molecules associated with BBB permeability (MMP-2, MMP-9, S100B), restoration (TIMP-1, TIMP-2, TSP-2), neuroinflammation (CCL-2), and endothelial activation (ICAM-1, P-sel) that are affected in epilepsy and can be measured in blood was selected in this study." (PMID 36766708, 2023). "Mmp9 and Timp1 were found to be overexpressed in neuronal and glial cells and are thought to be biomarkers of blood–brain barrier (BBB) dysfunction in animal models of epilepsy and clinical patients." (PMID 36104755, 2022). "We showed that serum levels of molecules associated with BBB disruption (MMP-2, MMP-9, S100B) and restoration (TIMP-1, TIMP-2) are increased in patients with epilepsy in the interictal period, which might reflect chronic processes taking place at the BBB, even in the absence of seizures." (PMID 36766708, 2023).
liver cirrhosis (9 papers, 2004 to 2024). "TIMP1 has been reported to be associated with tissue fibrosis, including liver cirrhosis." (PMID 36768545, 2023). "The TIMP-1 concentration in liver cirrhosis was higher than that in chronic hepatitis (p &lt; 0.01)." (PMID 14960203, 2004). "Notably, TIMP1 promotes tissue fibrosis in liver cirrhosis and lung fibrosis by influencing fibroblasts, which are essential in the cancer microenvironment, including those in haematologic malignancies." (PMID 36768545, 2023). "Tissue inhibitor of metalloproteinase 1 is highly induced during fibrosis in a number of animal models, such as bleomycin- and paraquat-induced lung fibrosis, and in human fibrotic diseases, such as IPF and liver cirrhosis, implicating TIMP1 and its upregulated expression in fibrosis development." (PMID 29872441, 2018).